AGTR1 (angiotensin II receptor type 1)
Diseases named in the same sentence as AGTR1 in open-access papers (continued):
Sharing a sentence is not in itself a finding about the gene and the disease.
essential hypertension (33 papers, 2008 to 2025). Hypertension that presents without an identifiable cause. "Among them, AGTR1, AKT1 with puerarin, EDNRA with tanshinone IIA, MAPK14 with daidzein, MAPK8 with ursolic acid, and CHRM2 with cryptotanshinone all have a strong correlation with GJD in the treatment of primary hypertension." (PMID 36046450, 2022). "The research uncovered that the key active ingredients of GJD in managing primary hypertension are puerarin, tanshinone IIA, daidzein, ursolic acid, and cryptotanshinone, which are mainly expected to contain a regulatory function in conjunction with AGTR1, AKT1, EDNRA, MAPK14, MAPK8, and CHRM2." (PMID 36046450, 2022).
liver fibrosis (31 papers, 2009 to 2026). "Angiotensin II is a potent inducer of liver fibrosis, as determined by experimental and clinical observations, and AGTR1 was recently implicated in the development of liver fibrosis via activation of JAK2." (PMID 29029395, 2017). "Downregulation of AGTR1 was closely associated with the progression of liver fibrosis, suggesting that H2S may inhibit the expression of AGTR1." (PMID 26034979, 2015). "Furthermore, H2S reduced the liver expression levels of AGTR1, which may be associated with the delayed progression of hepatic fibrosis." (PMID 26034979, 2015). "MF2 cells specifically expressed liver fibrosis-related genes AGTR1, CYGB, PIEZO2, and LPL, and MF5 cells specifically highly expressed immune-related genes TRAC, CD3D, GZMB, and FCGR3A." (PMID 40949143, 2025). "In fact, angiotensin-converting enzyme inhibitors and AT1-R blockers have been reported to improve liver fibrosis scores clinically, suggesting that the AGTR1-mediated pathway is involved in HSC activation." (PMID 29029395, 2017). "The results of the present study demonstrated that the protein expression levels of AGTR1 were negatively correlated with the degree of liver fibrosis." (PMID 26034979, 2015). "The present study aimed to investigate the effects of endogenous hydrogen sulfide (H2S) on the expression levels of angiotensin II type 1 receptor (AGTR1) in a rat model of carbon tetrachloride (CCl4)-induced hepatic fibrosis." (PMID 26034979, 2015). "In the model group, CCl4-induced hepatic fibrosis resulted in the significant upregulation of AGTR1 expression, as compared with the normal control group." (PMID 26034979, 2015). "Previous studies have demonstrated that the control of RAS activation by AGTR1 antagonists may have therapeutic potential in the treatment of hepatic fibrosis." (PMID 26034979, 2015). "The present study aimed to investigate whether H2S affects hepatic fibrosis by regulating the expression of AGTR1." (PMID 26034979, 2015). "Angiotensin II and AGTR1 interactions may play a pivotal role in liver fibrosis." (PMID 29029395, 2017). "Angiotensin II binds to the angiotensin II receptor type 1 (AT1) of mast cells resulting in the release of TGF-beta, further increasing liver fibrosis." (PMID 37764895, 2023). "The results indicated that the severity of hepatic fibrosis, the serum expression levels of HA, LN, PcIII, cIV, ALT, and AST, the liver expression levels of CSE and AGTR1, and the plasma expression levels of H2S were significantly higher in the PAG group, as compared with the model group (P<0.05)." (PMID 26034979, 2015). "In addition, the severity of hepatic fibrosis, the serum expression levels of HA, LN, PcIII, cIV, ALT, and AST, the liver expression levels of CSE and AGTR1, and the plasma expression levels of H2S were significantly lower in the NaHS group, as compared with the model group (P<0.05)." (PMID 26034979, 2015).
diabetic nephropathy (29 papers, 2009 to 2024). "Our data suggest that common variants in the AGTR1, ACE, and MTHFR genes are not strongly associated with diabetic nephropathy in our patients with type 1 diabetes." (PMID 39446857, 2024).
ovarian carcinoma (29 papers, 2006 to 2026). A malignant neoplasm originating from the surface ovarian epithelium. "The introduction of AGTR1 knockdown reversed the promotion effect of miR-140-3p inhibitor on the activation of MEK/ERK/STAT3 pathway in ovarian cancer cells, indicating the loss of AGTR1 expression can result in the inhibition of ovarian cancer progression." (PMID 34496800, 2021). "It is, however, interesting to note that BRCA1-mutated ovarian cancer as compared to their adjacent normal tissue reduced the expression of AGTR1 (P < 0.05)." (PMID 24321324, 2013). "Accumulating evidence also indicates that an increased risk of ovarian cancer and poor patient outcome are associated with AGTR1 expression." (PMID 24321324, 2013). "BRCA1 dysfunction (BRCA1 mutation or hypermethylated BRCA1 promoter) ovarian cancer showed decreased AGTR1 levels compared to normal tissue." (PMID 24321324, 2013). "Further, high AGTR1 levels are associated with poor epithelial ovarian cancer (EOC) outcomes." (PMID 30845964, 2019). "In contrast, AGTR1 expression was increased in non-BRCA1-mutated ovarian cancer." (PMID 24321324, 2013). "It has been reported that LINC00852/miR-140-3p/AGTR1 is an important pathway to promote the proliferation and invasion of ovarian cancer cells." (PMID 36983741, 2023). "AGTR1 stimulation meaningfully increased the formation of multicellular ovarian cancer spheroid development, cell migration, and peritoneal metastasis." (PMID 37291545, 2023). "According to one study, the expression of LINC00852 was highly up-modulated in ovarian cancer tissues, and it functioned as a ceRNA of miR-140-3p, promoting the expression of AGTR1 and activating the MEK/ERK/STAT3 signaling pathways." (PMID 35422758, 2022). "LINC00852/miR-140-3p/AGTR1 is an important pathway to promote the proliferation and invasion of ovarian cancer." (PMID 34496800, 2021). "The expressions of LINC00852, miR-140-3p and AGTR1 mRNA in ovarian cancer tissues and cells were detected by quantitative reverse transcription polymerase chain reaction (qRT-PCR) assay." (PMID 34496800, 2021). "In ovarian cancer, the frequency of AGTR1-positive cells is very high, with 85% of invasive adenocarcinomas expressing AGTR1." (PMID 30845964, 2019). "In this study, the molecular mechanism by which AGTR1 contributes to ovarian cancer has been identified." (PMID 30845964, 2019). "Since ANGII promotes MCS growth and metastasis of ovarian cancer cells, it is likely that ANGII and AGTR1 form a positive feedback loop that enhances ovarian cancer malignancy." (PMID 30845964, 2019). "The results were consistent with the GENT database in that AGTR1 was generally upregulated in ovarian cancer patients of four different studies." (PMID 30845964, 2019). "We used the data from the GENT database and immunohistochemistry staining to assess the AGTR1 expression in epithelial ovarian cancer (EOC) patients and to assess its role in cancer progression." (PMID 30845964, 2019). "That is, AGTR1 is expressed at a higher level in highly metastatic “mesenchymal subtype” ovarian cancer tissues." (PMID 30845964, 2019). "Taken together, these results suggest that higher expression of AGTR1 is likely to be greater in metastatic ovarian cancer cells." (PMID 30845964, 2019). "To understand the associations between the ANGII/AGTR1 pathway and cancer outcomes, we evaluated the effects of ANGII on MCS formation by ovarian cancer cells and used a proteomic approach to analyze the mechanistic basis." (PMID 30845964, 2019). "The Kaplan–Meier survival analysis suggested that high AGTR1 expression was negatively correlated with survival time of ovarian cancer patients." (PMID 30845964, 2019). "In a xenograft model, intraperitoneal (i.p.)injection of ANGII significantly increases the tumorigenicity and metastasis of ovarian cancer cells, whereas an AGTR1 antagonist, losartan, suppresses this effect." (PMID 30845964, 2019).
ovarian carcinoma (continued). "Both BRCA1 and angiotensin II type 1 receptor (AGTR1) play a critical role in ovarian cancer progression." (PMID 24321324, 2013). "Real-time PCR and immunohistochemical analysis showed that the levels of AGTR1 mRNA and protein were increased in non-BRCA1-mutated ovarian cancer compared to adjacent normal tissue (P < 0.05)." (PMID 24321324, 2013). "Of particular interest and potential clinical relevance, the relationship between BRCA1 and AGTR1 expression was studied in 63 human ovarian cancer specimens." (PMID 24321324, 2013). "Moreover, AGTR1 has been verified to promote the colony formation, migration and metastasis of ovarian cancer cells." (PMID 34496800, 2021). "In addition, miR-140-3p interacted with AGTR1 and negatively regulated its level in ovarian cancer cells." (PMID 34496800, 2021). "However, we only initially verified the regulatory mechanism of LINC00852/miR-140-3p/AGTR1 pathway in ovarian cancer." (PMID 34496800, 2021). "Besides, AGTR1 has been found to promote the proliferation, migration and metastasis of ovarian cancer by triggering ERK1/2 and AKT signaling pathways, and AGTR1 overexpression predicts a poor prognosis of ovarian cancer." (PMID 34496800, 2021). "Moreover, we found AGTR1 expression level was significantly up-regulated in ovarian cancer cells (SKOV-3, OV-90 and CAOV3) than normal human ovarian epithelial cells IOSE80." (PMID 34496800, 2021). "In the present study, we investigated the role of LINC00852/miR-140-3p/AGTR1 pathway in ovarian cancer, and found LINC00852 acted as a ceRNA of miR-140-3p to repress miR-140-3p expression thereby promoting AGTR1 expression to promote the growth and invasion of ovarian cancer in vitro and in vivo." (PMID 34496800, 2021). "Xenograft models were used to determine the role of AGTR1 in ovarian cancer metastasis." (PMID 30845964, 2019). "Moreover, we confirmed a correlation of AGTR1 expression with patient outcomes by using the TCGA RNA-seq data set that contains 294 ovarian cancer samples." (PMID 30845964, 2019). "Moreover, a proteomic approach was used to describe the molecular ANGII/AGTR1 axis in ovarian cancer and those data suggest that ANGII regulates lipid homeostasis." (PMID 30845964, 2019). "(a) AGTR1 upregulated in metastatic subtype of ovarian cancer patients." (PMID 30845964, 2019). "In summary, current data indicate that the study of AGTR1 pathways may reveal new avenues for the investigation of ovarian cancer pathogenesis." (PMID 30845964, 2019). "Herein, a role for ANGII and AGTR1 in ovarian cancer spheroid formation is identified." (PMID 30845964, 2019). "IHC is scored from 0 to 6+, as a measure of AGTR1 level in ovarian cancer tissue samples." (PMID 30845964, 2019). "Hence, a role for ANGII and AGTR1 in MCS formation was assessed with three ovarian cancer cell lines; Ovca429, A2780, and HM." (PMID 30845964, 2019). "In addition, ANGII was shown to stimulate ovarian cancer cell migration, with the migrated cells expressing higher AGTR1 than parental cells." (PMID 30845964, 2019). "Thus, elucidating the role of AGTR1 during ovarian cancer metastasis will prove integral to developing AGTR1-targeted drugs for the treatment of ovarian cancer." (PMID 28439256, 2017). "However, the molecular basis for how the ANGII/AGTR1 axis influences ovarian cancer is unclear." (PMID 30845964, 2019). "Our results indicate that BRCA1 may be a potential regulator of AGTR1 in ovarian cancer cells." (PMID 24321324, 2013). "In ovarian cancer, LINC00852 acts as the ceRNA of miR-140-3p to promote AGTR1 expression and activate the MEK/ERK/STAT3 pathway, thereby promoting the proliferation and invasion of ovarian cancer cells." (PMID 36983741, 2023). "There was a strong positive correlation between AGTR1 and SCD1 expression levels in ovarian cancer patients." (PMID 30845964, 2019). "Therefore, AGTR1 antagonists might be useful for suppressing tumor angiogenesis in ovarian cancer." (PMID 28439256, 2017).
ovarian carcinoma (continued). "GPCRs involved in cardiovascular function, such as AGTR1 and ETR, can also modulate the progression of ovarian cancer." (PMID 28439256, 2017). "Because ovarian cancer cells invade surrounding tissues through the peritoneal cavity, understanding the role of angiotensin II and ACE during metastasis will be essential to assess how AGTR1 regulates cancer progression." (PMID 28439256, 2017). "Notably, BRCA1 activation was an effective way to induce AGTR1 expression in primary ovarian cancer cells and a positive correlation exists between BRCA1 and AGTR1 expression in human ovarian cancer specimens." (PMID 24321324, 2013). "AGTR1 expression in ovarian cancer tissues was higher than in normal ovary tissue." (PMID 30845964, 2019). "Since i.p. injected ANGII may reach the peripheral organs, the observed effects of ANGII may be due to the activation of the AGTR1 pathway in peripheral organs, rather than by direct activation of ovarian cancer cells." (PMID 30845964, 2019). "Therefore, the present study was undertaken to investigate AGTR1 expression from genetic (BRCA1 mutated or not) and epigenetic (BRCA1 promoter methylated or not) aspects in ovarian cancer, and to provide novel insights into the regulatory mechanism of AGTR1." (PMID 24321324, 2013). "Interestingly, we observed that overexpression of BRCA1 was an effective way to induce an increase in AGTR1 levels in primary non-mutated and BRCA1-mutated ovarian cancer cells, although AGTR1 levels were not sensitive to the BRCA1 knockdown." (PMID 24321324, 2013).
Hyperglycemia (26 papers, 2011 to 2025). An increased concentration of glucose in the blood. "We have previously reported that hyperglycemia promotes A-II secretion in CRC cells, which enhances the progression of cancer through AGTR1 activation." (PMID 30564297, 2018).
prostate carcinoma (26 papers, 2006 to 2025). A carcinoma that arises from epithelial cells of the prostate gland. "In accordance with our results, AGTR1 was expressed at low levels in tumor tissues in 73 pairs from more than 14 tumor types but overexpressed in normal tissues in a set of prostate cancer pairs." (PMID 34671200, 2021). "Taken together, AngII–AGTR1 signalling pathways play a critical role in the pathogenesis of AGTR1-positive breast and prostate cancer." (PMID 25981295, 2015). "In addition, AGTR1 has been identified to be the upstream molecule of MEK/ERK/STAT3 pathway in regulating the growth and metastasis of prostate cancer." (PMID 34496800, 2021).
coronary artery disease (25 papers, 2009 to 2025). "The AGTR1 gene encodes angiotensin II receptor type 1, which is involved in cardiovascular diseases such as coronary heart disease (CHD)." (PMID 31538912, 2020). "The authors conclude that there is only a weak association between the AGTR1 c.1080*86A>C polymorphism and coronary heart disease." (PMID 22307319, 2012). "The aim of our study is to evaluate the relationship between angiotensin II type-1 receptor (AGTR1) gene rs3772622 polymorphisms and the risk of developing coronary artery disease (CAD) in Chinese patients with NAFLD." (PMID 27342049, 2016). "One example of such investigations is the meta analysis on the A1166C variant of the angiotensin II type 1 receptor (AGTR1) and its association to coronary heart disease (CHD), encompassing 53 studies including 20,435 cases and 23,674 controls and covering a total study time of 15 years." (PMID 24904262, 2014). "A number of drugs used for the treatment of hypertension, hypercholesterolaemia and coronary artery disease such as the statins, AT1 (angiotensin II receptor type 1) antagonists and ACE inhibitors have been shown to decrease NADPH oxidase-derived superoxide and ROS production." (PMID 20953160, 2010).
lung fibrosis (25 papers, 2004 to 2025). "Thus, cooperation and amplification of pro-fibrotic effects between TGFβ and AGTR1 are likely to be implicated in lung fibrosis." (PMID 15571627, 2004). "This study identifies several novel TGFβ targets in lung fibroblasts, and confirms with independent methods the induction of angiotensin II receptor type 1, underlining a potential role for angiotensin II receptor 1 antagonism in the treatment of lung fibrosis." (PMID 15571627, 2004). "Future studies are needed to better understand the mechanisms of Myosin IIB accumulation and to evaluate the efficacy of AGTR1 inhibitors in animal models of HPS pulmonary fibrosis." (PMID 35739508, 2022). "Further studies are needed to assess the functional effects of AGTR1 stimulation in lung fibroblasts and to evaluate the biological role of AGTR1 in lung fibrosis." (PMID 15571627, 2004). "Compared to controls, lung fibroblasts from patients with idiopathic pulmonary fibrosis produce higher levels of angiotensin II, shown to induce apoptosis in alveolar epithelial cells through AGTR1." (PMID 15571627, 2004). "Immunohistochemical staining showed AGTR1 expression by lung fibroblasts in fibroblastic foci within biopsies of idiopathic pulmonary fibrosis." (PMID 15571627, 2004). "We assessed staining for AGTR1 in lung biopsies from four patients with idiopathic pulmonary fibrosis and compared it to that of three control lungs." (PMID 15571627, 2004). "Blockade of angiotensin II or of AGTR1 attenuates lung collagen deposition in animal models of lung fibrosis." (PMID 15571627, 2004). "Both in control and in idiopathic pulmonary fibrosis lung biopsies, AGTR1 immunoreactivity was observed in alveolar epithelial cells and alveolar macrophages." (PMID 15571627, 2004).
aortic aneurysm (21 papers, 2011 to 2025). A ruptured aneurysm located in the wall of the proximal portion of the descending aorta proceeding from the arch of the aorta. "While losartan effectively reduces the progression of aortic aneurysm in Marfan syndrome by blocking AGTR1 and inhibiting TGF-beta signaling, it has been proven that losartan does not improve the biomechanical integrity of the thoracic aorta in the vEDS mouse model." (PMID 40559232, 2025).
Alzheimer disease (20 papers, 2016 to 2025). A progressive, neurodegenerative disease characterized by loss of function and death of nerve cells in several areas of the brain leading to loss of cognitive function such as memory and language. "One of these compounds, the angiotensin II receptor type 1 antagonist Losartan, was shown to efficiently prevent the pathogenic intra-CNS overproduction of TGF-beta 1 involved in post-stroke epilepsy and in Alzheimer’s disease." (PMID 31779094, 2019). "In the process of normal aging, heightened signaling from ACE1/AGTR1 expression is predominantly countered by ACE1/AGTR2 expression, while the levels of ACE2, MAS1, and LNPEP remain constant, while in the later stages of Alzheimer’s disease, a decline in MAS1 expression emerges." (PMID 41303587, 2025).
pancreatic cancer (20 papers, 2006 to 2026). "Downregulation of miR-410 was detected in pancreatic cancer samples, although there was high expression of AGTR1 in this cancer." (PMID 34095461, 2021). "They concluded that miR-410 inhibited cell migration, growth, invasion, and angiogenesis by reducing AGTR1 expression in pancreatic cancer." (PMID 34095461, 2021).
aneurysm (19 papers, 2011 to 2024). Bulging or ballooning in an area of an artery secondary to arterial wall weakening. "The walls of aneurysms show less presence of the angiotensin converting enzyme (ACE) and angiotensin II receptor type 1 (AT1), which causes a thinning of the arterial wall and a lack of vascular remodeling." (PMID 36499752, 2022). "Luciferase report assays demonstrated that miRNA-155 could bind directly to the 3′ UTR of angiotensin II receptor type 1 (AGTR1), which was associated with aneurysm formation." (PMID 28018919, 2016). "Angiotensin II receptor type 1 (AT1) signaling stimulates proliferation of VSMC and vascular fibrosis, while the AT1 receptor blocker Losartan has been shown to reduce experimental aneurysm formation in mouse models of Marfan's disease." (PMID 22400124, 2012).